HOTAIR (HOX transcript antisense RNA)
Diseases named in the same sentence as HOTAIR in open-access papers (continued):
Sharing a sentence is not in itself a finding about the gene and the disease.
pancreatic cancer (continued). "Compared with benign pancreatic tumour (BPT) and normal pancreatic tissues (NPT), HOTAIR, HOTTIP and PVT1 were significantly up-regulated in pancreatic cancer tissues (PCT)." (PMID 27028998, 2016). "Compared with normal pancreatic tissues (NPT), the expression of HOTAIR, HOTTIP, and PVT1 exhibited significant elevation in pancreatic cancer tissues (PCT) (p values were 0.025, 0.006, and 0.016, respectively)." (PMID 27028998, 2016). "In summary, our studies demonstrated that miR-663b is epigenetically repressed by HOTAIR and exerts its tumor-suppressive function via targeting IGF2 in pancreatic cancer." (PMID 27895308, 2016). "HOTAIR promotes PACN-1 CSC self-renewal ability, growth, and migration by inhibiting the chemosensitivity of PACN-1 CSCs, supporting its potential as a new therapeutic target for pancreatic cancer." (PMID 36100611, 2022). "A ceRNA network profile has identified the several lncRNAs for classifying diabetic pancreatic cancer form non-diabetic pancreatic cancer, including HOTAIR, CECR7, UCA1, suggesting that lncRNAs are important predictors for diabetic pancreatic cancer." (PMID 36313695, 2022). "In vitro mechanistic studies have revealed that miR-663b activity can be blocked by its interaction with HOTAIR, suggesting that miR-663b is epigenetically repressed by HOTAIR and exerts its tumor suppressive function via targeting of IGF2 in pancreatic cancer." (PMID 33540611, 2021). "HOTAIR could transcriptionally regulate the expression of hundreds of genes in both PRC2-dependent and PRC2-independent manner in pancreatic cancer cells." (PMID 34439315, 2021). "HOTAIR inhibits the expression of cell cycle interferon related genes, targets and binds to the tumor suppressor gene GDF15, and accelerates the proliferation of pancreatic cancer cells." (PMID 32257946, 2020). "HOTAIR is a long intervening non-coding RNA (lincRNA) whose expression is increased in pancreatic tumors compared to non-tumor tissue." (PMID 30309340, 2018). "Recently, HOTAIR has been determined to be a negative prognostic indicator in breast, colon, liver, and pancreatic cancer patient survival, and increased HOTAIR expression in patients has been correlated with enhanced breast and colon cancer metastasis." (PMID 24103700, 2013). "Also, after radiotherapy, HOTAIR down-expression by overexpression of Wnt inhibitory factor 1 (WIF-1) and autophagy related 7 (ATG7) reduces radio-resistance and cell proliferation and induces apoptosis in pancreatic cancer patients." (PMID 38559560, 2024). "Similarly, UCA1 was found to be a robust prognostic marker for diabetic pancreatic cancer, whilst both HOTAIR and UCA1 were involved in separate lncRNA/miRNA/lncRNA “competitive triples” that could stratify diabetic and non-diabetic pancreatic cancer patients with high accuracy." (PMID 29702599, 2018).
prostate carcinoma (61 papers, 2014 to 2025). A carcinoma that arises from epithelial cells of the prostate gland. "Studies had also shown that GAS5 rs145204276 and HOTAIR rs4759314 polymorphisms affected the expression of GAS5 and HOTAIR, affecting the survival rates of prostate cancer." (PMID 33391419, 2021). "Meanwhile, HOTAIR has been extensively studied as an oncogene, and functional SNPs in HOTAIR are associated with cancer risk, including lung, gastric, esophageal, cervical, breast, and prostate cancers." (PMID 36924407, 2023). "Furthermore, miR-34a binding to HOTAIR results in knockdown of HOTAIR, thus causing a decrease in prostate cancer cell growth and metastasis." (PMID 28272374, 2017). "Given the key role played by eNOS in the progression of PCa, it is conceivable that the association HOTAIR/eNOS and the HOTAIR/ERβ/eNOS complex on chromatin (as assessed by RNA-Re-ChIP) appears to be an essential molecular feature associated with advanced prostate cancer." (PMID 27922078, 2016). "Expression of hepaCAM was inversely related to the HOTAIR in prostate cancer due to repression of hepaCAM promotor by HOTAIR-mediated recruitment of PRC2 and downregulation of hepaCAM promoted metastasis by the abnormal activation of MAPK signalling pathway." (PMID 40176927, 2024). "In prostate cancer, a study demonstrated that HOTAIR promotes the invasion and metastasis of PCa by decreasing the inhibitory effect of hepaCAM on MAPK signaling." (PMID 36924407, 2023). "We also examined the expression levels of ProT and HOTAIR in different urothelial carcinoma cell lines, including six bladder cancer, one prostate cancer (PC3), one renal cancer (BFTC909), and one normal uroepithelial (SV-HUC-1) cell lines." (PMID 36471329, 2022). "HOTAIR influences the apoptosis and cell cycle in prostate cancer cells and miR-34A regulates the expression of HOTAIR." (PMID 34209224, 2021). "In both DU145 and PC-3 prostate cancer cells, HOTAIR was directly targeted by genistein and it also upregulated miR-34a expression." (PMID 34336089, 2021). "Several studies have described the functional interaction between HOTAIR and miRNAs in prostate cancer development and progression." (PMID 33540611, 2021). "HOTAIR is upregulated by genistein in castration-resistant prostate cancer cell lines and its knockdown decreases cell proliferation, migration, and invasion, and induces apoptosis and cell cycle arrest." (PMID 33540611, 2021). "In prostate cancer, HOTAIR upregulation promotes cell growth and invasion by blocking the degradation of androgen receptor (AR) protein to which it binds." (PMID 33540611, 2021). "On the other hand, miR-193a directly targets HOTAIR and reduces its expression in prostate cancer cells." (PMID 33540611, 2021). "Another studies has reported that downregulating HOTAIR degraded DNMT1 protein expression in prostate cancer cells and osteosarcoma cells." (PMID 33941772, 2021). "Cell proliferation, cell cycle arrest, apoptosis, and migration of prostate cancer cells were decreased due to inhibition of HOTAIR." (PMID 34336089, 2021). "Prostate cancer cell growth was also affected by inhibiting oncogenic HOTAIR which is influenced by tumor suppressor miR-34a." (PMID 34336089, 2021). "HOTAIR, a lncRNA, has been reported to enhance the androgen receptor-mediated transcriptional program and drive castration-resistant prostate cancer." (PMID 33808801, 2021). "To investigate the role of HOTAIR in prostate cancer development, we first analyzed its expression levels based on TCGA dataset (GSE35988)." (PMID 32657763, 2020). "Collectively, these findings suggest that contribution of HOTAIR to prostatic cancer stemness is at least partly due to STAT3 activation." (PMID 32657763, 2020). "Recent studies propose that several lncRNAs including LOXL1-AS1, PVT1, and HOTAIR exhibit abnormal expression in prostate cancer." (PMID 32440687, 2020).
prostate carcinoma (continued). "In urological cancers, HOTAIR overexpression is able to increase prostate cancer cells growth and invasion by binding androgen receptor (AR) protein and blocking its degradation." (PMID 32397382, 2020). "A recent report showed that lncRNA HOTAIR expression was increased in castration-resistant prostate cancer cells, and HOTAIR is involved in prostate cancer cell biological functions." (PMID 33013201, 2020). "Similar results were gained by another research that MIR193A is downregulated in metastatic prostate cancer and is involved in HOTAIR/EZH2/miR-193a feedback loop to exert a tumor suppressive function in prostate cancer." (PMID 31523496, 2019). "For example, HOTAIR would induce androgen-independent (AR) activation, which plays a central role in establishing an oncogenic cascade that drives prostate cancer progression." (PMID 31760932, 2019). "Based upon our proposed method, prostate cancer was predicted to be associated with H19, MALAT1, CDKN2B-AS1, HOTAIR, PCAT1, SRA1, XIST." (PMID 29671405, 2018). "We also illustrated a interesting cross-regulation between miR-193a and oncogene HOTAIR that miR-193a directly targets HOTAIR and modulates its expression in prostate cancer." (PMID 29141691, 2017). "Genistein showed promising results, inhibiting the expression of HOTAIR (HOX transcript antisense RNA) in prostate cancer cell lines, an oncogenic lnRNA that is highly expressed in this type of malignancy." (PMID 28587155, 2017). "A report on prostate cancer suggested that the interaction between miR-34a and HOTAIR, a well-conserved lncRNA, can mitigate the oncogenic effect of HOTAIR." (PMID 28272374, 2017). "The clinical expression of these genes in tumor tissues further verified the regulatory mechanism of HOTAIR/EZH2/miR-193a feedback loop in prostate cancer." (PMID 29141691, 2017). "Altogether, above results clearly indicate that miR-193a directly targets HOTAIR and negatively modulates HOTAIR expression in prostate cancer." (PMID 29141691, 2017). "In summary, we found that miR-193a is downregulated in metastatic prostate cancer and plays tumor suppressive function in prostate cancer, which was attributed to HOTAIR mediated EZH2 targeting to the promoter of miR-193a." (PMID 29141691, 2017). "MiR-34a binds directly to HOTAIR and represses expression levels of HOTAIR in prostate cancer cells." (PMID 27121316, 2016). "To gain deeper insight into HOTAIR function in ER signaling, we next evaluated the consequences of HOTAIR depletion by gapmers on the estrogen responsiveness in prostate cancer cells transfected with specific or scramble oligonucleotides." (PMID 27922078, 2016). "In fact, knockdown of HOTAIR decreased prostate cancer cell proliferation, migration, invasion, and induced apoptosis and cell cycle arrest." (PMID 26978351, 2016). "A recent study, however, recorded down-regulation of HOTAIR expression in prostate cancer cells mediated by miR-34a45 and this miRNA has been reported to be differentially expressed in CaCx cases as well." (PMID 26152361, 2015). "miR-34a reduces the expression of HOTAIR and a reporter gene that is controlled by the miR-34a target site from HOTAIR in prostate cancer cells." (PMID 25491133, 2014). "A relationship between HOTAIR and other types of tumors, including lung cancer, prostate cancer, pancreatic carcinoma, and sarcoma, has been reported." (PMID 25334066, 2014). "HOTAIR is also involved in regulating proliferating renal cell carcinomas and can control the transcription of androgen receptor targets, contributing to a more resistant response to antiandrogens in prostate cancer." (PMID 38095719, 2024). "In prostate cancer, HOTAIR elevated the quantity of CSCs by activating the STAT3 signal pathway." (PMID 36100611, 2022).
prostate carcinoma (continued). "Notable examples associated with aggressive cancer and adverse outcomes include HOTAIR (HOX transcript antisense RNA), which is upregulated in a range of cancers, and the prostate cancer-specific SCHLAP1 (SWI/SNF Complex Antagonist Associated With Prostate Cancer 1)." (PMID 33585078, 2021). "Furthermore, HOTAIR is negatively correlated with the expression of miR-152 during prostate cancer evolution." (PMID 33540611, 2021). "Therefore, we concluded that hepaCAM acts as a key bridge molecule in the process of distant metastasis that is altered by HOTAIR in prostate cancer." (PMID 33024272, 2021). "In fact, HOTAIR upregulation induced the expression of some NEPC markers in prostate cancer cells." (PMID 34576322, 2021). "These discoveries indicate that HOTAIR could serve as an attractive target for the treatment of docetaxel-insensitive prostate cancer." (PMID 33024272, 2021). "Moreover, HOTAIR silencing is able to increase radio sensitivity and influence autophagy in prostate cancer cells." (PMID 32397382, 2020). "The up-regulated HOTAIR promotes cell proliferation of prostate cancer cells." (PMID 32242897, 2020). "In prostate cancer, genistein reduced the HOTAIR and miR-34a expression synergically." (PMID 31208095, 2019). "Interestingly, estradiol is able to induce the expression of HOTAIR via direct binding with estrogen response elements, while the estradiol inhibitor genistein downregulates the level of HOTAIR in prostate cancer cells." (PMID 28649178, 2017). "Accumulating evidence indicate that HOTAIR may function as an oncogene in the malignant progression of various cancers including prostate cancer, indicating its potential role of effective therapeutic target in cancers." (PMID 29141691, 2017). "Thus, the tumor suppressor miR-193a was continuously inhibited and oncogene HOTAIR remained highly expressed in prostate cancer, which promoting initial prostate cancer developed into highly aggressive cancer type." (PMID 29141691, 2017). "In other cancer types such as renal cancer, colorectal adenocarcinoma and prostate cancer, HOTAIR was down-regulated by miR-141, but whether this mechanism of HOTAIR regulation exists in PC is unknown." (PMID 27429196, 2016). "Moreover, the level of HOTAIR continually increased in prostate cancer cell lines upon treatment with enzalutamide, suggesting HOTAIR might serve as a biomarker indicating resistance against enzalutamide." (PMID 34367966, 2021). "HOTAIR contributes to Polyphyllin I-inhibited growth of castration-resistant prostate cancer cells by regulating DNMT1 and EZH2 in prostate cancer." (PMID 34405017, 2021). "In prostate cancer cells, EZH2 interacts with HOTAIR to silence miR-193a, a tumor suppressor miRNA, through the introduction of tri-methylation of H3K27 at the miR-193a promoter region." (PMID 33540611, 2021). "Other lncRNAs, such as PCGEM1, HOTAIR, and AK001796, were overexpressed in most cases of prostate cancer and phytochemical-induced anticancer activities." (PMID 31208095, 2019). "As examples, the regulatory mechanism of HOTAIR in prostate cancer was to sponge miR-152 to increase the expression of FOXR2, modulating proliferation and apoptosis of prostate cancer cells." (PMID 31889897, 2019). "As to prostate cancer, two top-ranked lncRNAs UCA1 and HOTAIR have been actually stored in the lnc2cancer database." (PMID 29108274, 2017). "HOTAIR, one of the most well-known and studied lncRNA, was firstly found to recruit PRC2 in modulating the cancer epigenome in prostate cancer which depend on the enzymatic activity of EZH2." (PMID 27835578, 2016). "HOTAIR depletion regenerated hepaCAM levels in the cells and restricted cancer growth and metastasis, indicating HOTAIR/hepaCAM/MAPK axis to be a potential therapeutic roadway for prostate cancer." (PMID 40176927, 2024).
prostate carcinoma (continued). "To date, a variety of transcriptional substances in urinary exosomes have been found to play a role in prostate cancer and are potentially attractive in terms of prostate cancer biomarkers, e.g., PCA3, MALAT1, HOTAIR, miR-1290, and miR-375 are some of the more common markers." (PMID 39090720, 2024). "In prostate cancer, propofol strengthened PTX sensitivity by regulating HOTAIR-mediated EMT." (PMID 36100611, 2022). "LncRNAs MALAT1 and HOTAIR not only serve as transcriptional targets of miRNAs but are also involved in the regulation of hormone‐sensitive genes, such as PSA, hTERT and pS2, that are targeted by oestrogen in prostate cancer cells." (PMID 33733597, 2021). "Several lncRNAs have been used as diagnostic and prognostic markers, including the following: MALAT-1 for liver, lung, breast, and prostate cancer; HOTAIR for breast, brain, and colon cancer; OOC1 for colon cancer; and PCA3, PCAT-1, and SChLAP1 for prostate cancer." (PMID 26160837, 2015). "Therefore, the HOTAIR/hepaCAM/MAPK axis may provide a new avenue towards therapeutic strategies and prognostic indicators for advanced prostate cancer." (PMID 33024272, 2021).
glioblastoma (55 papers, 2015 to 2025). The most malignant astrocytic tumor (WHO grade IV). "Further, based upon data from clinical cases of glioblastoma with and without temozolomide resistance, the authors advocated the employment of serum exosomal HOTAIR expression as a diagnostic biomarker for temozolomide sensitivity of glioblastomas." (PMID 38366205, 2024). "Consistent with our data, the cellular lncRNA HOTAIR was described to interact with EZH2 in glioblastoma, thus linked to tumor dissemination, PMT, and drug resistance." (PMID 37147437, 2023). "HOTAIR is implicated in the cell cycle process in glioblastoma while silencing HOTAIR declines proliferation and promotes apoptosis of synoviocytes in osteoarthritis." (PMID 35248107, 2022). "Hox Transcript Antisense Intergenic RNA (HOTAIR), a potential biomarker of glioblastoma, is highly expressed in glioblastoma and is associated with poor prognosis." (PMID 28410200, 2017). "Circulating levels of HOTAIR are significantly correlated with high‐grade brain tumors, and one study demonstrated that this lncRNA could be considered a novel prognostic and diagnostic biomarker for glioblastoma." (PMID 34316694, 2021). "This exosome-mediated transfer of HOTAIR contributes to the spread of chemoresistance across glioblastoma cells." (PMID 40781643, 2025). "Another study based upon data from TCGA database proposed HOTAIR as a prominent lncRNA with robust elevations in the expression levels in glioblastoma subjects." (PMID 38366205, 2024). "Evaluation of the molecular mechanisms underlying the anti-oncological effects of BET bromodomain inhibitor I-BET151 in glioblastoma LN18 cells has revealed the significance of abrogation of hyperactivation of HOTAIR lncRNA." (PMID 38366205, 2024). "The crucial role of HOTAIR in the induction of temozolomide (TMZ) resistance in glioblastoma cells has been also described." (PMID 38887279, 2024). "The lncRNA HOTAIR, an oncogene identified in gliomas, was involved in angiogenesis via its transmission into ECs through Glioblastoma-EVs, a process that requires VEGFA induction." (PMID 38379858, 2024). "HOTAIR expression was found to be significantly increased in temozolomide resistant glioblastoma cells, and its silencing culminated into regularized vulnerability of the cell and in vivo xenograft tumors to temozolomide." (PMID 38366205, 2024). "The main function of HOTAIR in glioblastoma is to promote cell proliferation and migration, and inhibit cell apoptosis." (PMID 36924407, 2023). "In glioblastoma, the HOTAIR gene locus can undergo histone modifications, such as increased levels of H3K27me3." (PMID 38003512, 2023). "We herein investigate the therapeutic potential of bioinformatically identified HOTAIR transferred by serum-derived EVs (serum-EVs) in temozolomide (TMZ) resistance of glioblastoma (GBM) and the downstream mechanisms." (PMID 35418162, 2022). "Conversely, HOTAIR overexpression in conjunction with I‐BET151 treatment abrogated the BET bromodomain inhibitor's anti-proliferative activity in glioblastoma cells." (PMID 34316694, 2021). "Cell cycle and proliferation: HOTAIR is required for the formation of glioblastoma and influenced the cell cycle by regulating molecules having a role in its different phases." (PMID 34322395, 2021). "Expression of HOTAIR has been elevated in TMZ-resistant glioblastoma cells and its silencing has suppressed proliferation, migration, invasion, and EMT in TMZ-resistant cells." (PMID 34178658, 2021). "Concomitantly, the protein expression level of Cyclin D1 declined significantly suggesting that HOTAIR can repress the proliferation and promote the apoptosis of glioblastoma cells by targeting miR-219." (PMID 34576322, 2021). "Our past research confirmed that HOTAIR promotes glioblastoma cell cycle progression in an EZH2-dependent manner." (PMID 34082742, 2021).